NKD1 (NKD inhibitor of Wnt signaling pathway 1)
Description:
Cell autonomous antagonist of the canonical Wnt signaling pathway. May activate a second Wnt signaling pathway that controls planar cell polarity.
Synonyms: Naked1
Tractability: Antibody: UniProt places it where antibodies can reach, with medium confidence; its Gene Ontology location is reachable by antibodies, with medium confidence.
Gene: Protein-coding gene on chromosome 16 (50,548,396 to 50,649,249, forward strand). Ensembl gene ENSG00000140807.
Subcellular location: Cell membrane; Cytoplasm
Subcellular location (Human Protein Atlas): Nucleoli fibrillar center
Gene Ontology:
Molecular function: protein binding; calcium ion binding; PDZ domain binding
Biological process: negative regulation of canonical Wnt signaling pathway; positive regulation of protein catabolic process; axis elongation; eye photoreceptor cell differentiation; negative regulation of Wnt signaling pathway; positive regulation of non-canonical Wnt signaling pathway; positive regulation of Wnt signaling pathway, planar cell polarity pathway; regulation of cell migration involved in somitogenic axis elongation; somatic muscle development; convergent extension; positive regulation of MAPK cascade
Cellular component: protein phosphatase type 2A complex; cytoplasm; plasma membrane
Genetic constraint (gnomAD): Loss-of-function variants: 20 observed, 41.04 expected, observed/expected ratio (o/e) 0.49, 90% interval 0.34 to 0.71. The upper end of that interval is the gene's LOEUF score, 0.71, which puts it in group 2 of 6, group 1 being the genes least tolerant of losing a copy. Missense variants: 545 observed, 586.08 expected, observed/expected ratio (o/e) 0.93, 90% interval 0.87 to 1. Synonymous variants: 250 observed, 240.13 expected, observed/expected ratio (o/e) 1.04, 90% interval 0.94 to 1.16.
Homologues: Orthologues: chimpanzee NKD1 (99% identical), pig NKD1 (89% identical), dog NKD1 (88% identical), macaque NKD1 (87% identical), mouse Nkd1 (87% identical), guinea pig NKD1 (87% identical), rabbit NKD1 (76% identical), tropical clawed frog nkd1 (54% identical), zebrafish nkd1 (49% identical), Drosophila melanogaster nkd (24% identical), Drosophila melanogaster PIP82 (19% identical). Paralogues in human: NKD2 (42% identical).
Diseases named in the same sentence as NKD1 in open-access papers:
NKD1 is named in the same sentence as 56 diseases in open-access papers, as found by Europe PMC text mining. Sharing a sentence is not in itself a finding about the gene and the disease. The quoted sentences say what the papers report.
colon carcinoma (8 papers, 2011 to 2025). "These discoveries provide new insights into the function and underlying mechanism of NKD1 in the colon cancer cells." (PMID 34547189, 2021). "However, the underlying mechanism by which NKD1 enhances the progression of colon cancer remains obscure." (PMID 40675969, 2025). "To explore the underlying mechanisms by which NKD1 involved in the Wnt/β‐catenin signal pathway in colon cancer cells, we first wondered whether NKD1 regulated the binding affinity between Dvl and β‐catenin." (PMID 34547189, 2021). "In brief, the EF-hand domain is a key component of NKD1 in blocking the apoptosis of colon cancer cells." (PMID 40675969, 2025). "PPARδ overexpression with NKD1 gene knockdown markedly impeded the migration of colon cancer cells, indicating that PPARδ enhances colon cancer cell migration via NKD1." (PMID 40675969, 2025). "Further study revealed that the MYC protein was degraded mainly through the autophagy pathway in colon cancer cells and that NKD1 restrained this process by suppressing the interaction between LC3B and MYC proteins." (PMID 40675969, 2025). "Functionally, the PPARδ/NKD1/MYC signaling pathway increased colon cancer cells’ proliferation, migration and angiogenesis capabilities." (PMID 40675969, 2025). "PPARδ promoted the proliferation and migration of colon cancer cells by increasing NKD1 transcription." (PMID 40675969, 2025). "We found that PPARδ is a transcription factor of the NKD1 gene, and our previous studies demonstrated that NKD1 promotes colon cancer cell proliferation and migration." (PMID 40675969, 2025). "For example, NKD1 enhances the proliferation and migration of colon cancer cells while inhibits hepatocellular carcinoma cell proliferation." (PMID 37857014, 2023). "In the present study, we first confirmed that NKD1 was well expressed in the colon carcinoma tissues and colon cancer cells, which was consistent with the published paper." (PMID 34547189, 2021). "Expressions levels of NKD1 in colon carcinoma tissues were further confirmed by immunohistochemical staining and western blot assays." (PMID 34547189, 2021). "Clone formation assays demonstrated that the numbers of clones of SW620‐nkd1−/− cells were notably reduced than that of parental SW620 cells, suggesting that NKD1 knockout remarkably inhibited the growth of colon cancer cells." (PMID 34547189, 2021). "The tumors generated from SW620‐nkd1−/− cells were notably smaller than those of parental SW620 (WT) cells, implying that NKD1 knockout significantly restrained the proliferation of colon cancer cells." (PMID 34547189, 2021). "NKD1 expression levels in different cancer cells inferred that NKD1 expressed in colon cancer SW620 and HT29 cells were relatively higher than that in the HEK293T, SW480, and HELA cells measured by western blot." (PMID 34547189, 2021). "Our previous results displayed that NKD1 had the function of promoting the proliferation of colon cancer cells, which seemed to be contradicted with the published papers." (PMID 34547189, 2021). "NKD1 knockdown or knockout remarkably inhibited the growth of colon cancer cells in vitro and in vivo, which were contrary to the result that NKD1 was an antagonist of the Wnt signaling pathway." (PMID 34547189, 2021). "In order to further verify the proliferation function of NKD1 in vivo, the colon cancer SW620‐nkd1−/− cell was constructed by knocking out nkd1 gene through Crispr Cas9 technology." (PMID 34547189, 2021). "The two NKD1 siRNA were then transfected into the colon cancer SW620 cells to perform the EdU experiments and MTT assays, respectively." (PMID 34547189, 2021). "We found that NKD1, one of the core genes highly expressed in the colorectal carcinoma samples, promoted the proliferation of colon cancer cells in vitro and in vivo." (PMID 34547189, 2021). "We believe that NKD1 well expressed in the colorectal carcinoma tissues can enhance the proliferation of colon cancer cells." (PMID 34547189, 2021).
colon carcinoma (continued). "We found a novel function of NKD1 in promoting the proliferation of colon cancer cells, and a fresh mechanism proposing NKD1‐mediated regulation of β‐catenin durability in colon cancer cells." (PMID 34547189, 2021). "The numbers of EdU stained cells transfected with NKD1 siRNA‐1 or siRNA‐2 were significantly reduced relative to that of cells transfected with NC siRNA, which implied that NKD1 knockdown suppressed the proliferation of colon cancer SW620 cells." (PMID 34547189, 2021). "NKD1 knockout remarkably decreased the expression of β‐catenin and notably inhibited its nuclear accumulation, which resulted in the suppression of colon cancer proliferation." (PMID 34547189, 2021). "Moreover, our previous studies indicated that NKD1 is highly expressed in colorectal carcinoma tissues and promotes the proliferation and migration of colon cancer cells." (PMID 40675969, 2025). "In summary, NKD1 inhibits the autophagy signaling pathway in colon cancer cells." (PMID 40675969, 2025). "The expression levels of the MYC protein in SW620-nkd1−/− cells treated with CHX and CQ were notably greater than those in the cells treated with only CHX, indicating that NKD1 gene knockout considerably increases MYC protein autophagic degradation in colon cancer cells." (PMID 40675969, 2025). "We next investigated whether PPARδ could promote colon cancer cell proliferation and migration by activating NKD1 transcription." (PMID 40675969, 2025). "Therefore, the expression of NKD1 in colon cancer cells is significantly positively correlated with the expression of the β-catenin gene in the classical Wnt pathway." (PMID 40675969, 2025). "Because MYC is a widely researched oncoprotein, we investigated whether NKD1 stimulates colon cancer progression through MYC." (PMID 40675969, 2025). "NKD1, one of the hub genes, highly expressed in the colon carcinoma tissues could enhance the proliferation of colon cancer cells." (PMID 34547189, 2021). "Moreover, the immunohistochemical staining assays indicated that NKD1 expressed highly in the colon carcinoma specimen compared with the colon normal tissues." (PMID 34547189, 2021). "We then further explored the possible function of NKD1 in the colon cancer cells." (PMID 34547189, 2021). "MTT results also evidenced that OD values of the cells transfected with NKD1 siRNA‐1 or siRNA‐2 declined notably compared with the cells transfected with NC siRNA, which suggested that NKD1 knockdown could inhibit the proliferation of colon cancer cells." (PMID 34547189, 2021). "NKD1 was highly expressed in the colon cancer SW620 cells, to explore the potential functions NKD1 might have in colon cancer cells, two different NKD1 siRNA were designed and transfected into the colon cancer SW620 cells." (PMID 34547189, 2021). "Taken together, NKD1 well expressed in colorectal tumor samples and colon cancer cells, implying that NKD1 could have important functions in the colon cancer cells." (PMID 34547189, 2021). "However, NKD1 gene highly expressed in the colon cancer samples, which was consistent with our bioinformatics analysis results." (PMID 34547189, 2021). "Taken together, NKD1 knockout remarkably reduced the β‐catenin expression and inhibited its nuclear accumulation, which further inhibited the Wnt/β‐catenin signal pathway and finally suppressed the proliferation of colon cancer cells." (PMID 34547189, 2021). "In addition, the data showed that SW620‐nkd1−/− cells displayed a notable decrease in both tumor weights and tumor volumes compared with parental SW620 cells, which implied that NKD1 knockout significantly suppressed the tumorigenesis of colon cancer cells." (PMID 34547189, 2021). "However, the functions and involved mechanisms of NKD1 in the colon cancer cells are presently obscure." (PMID 34547189, 2021).
colon carcinoma (continued). "Relative to the control cells, the half‐life of β‐catenin proteins in HCT116 cells overexpressed NKD1 was obviously prolonged, signifying that NKD1 could stabilize β‐catenin in the colon cancer cells." (PMID 34547189, 2021). "Therefore, NKD1 may serve as a specific biomarker for colon cancer and a potential new target for tumor treatment." (PMID 40675969, 2025). "However, our previous study revealed that NKD1 could promote the proliferation and migration of colon cancer cells, enhancing colon cancer progression via unknown mechanisms." (PMID 40675969, 2025). "Furthermore, NKD1 notably increases MYC protein expression in colon cancer cells." (PMID 40675969, 2025). "We thought that this might be the specific regulation of NKD1 in colon cancer cells." (PMID 34547189, 2021). "Importantly, the stability of β‐catenin proteins was maintained by NKD1 in the colon cancer cells." (PMID 34547189, 2021). "We then wondered whether NKD1 expression could regulate the expression of β‐catenin, western blot results showed that NKD1 knockout notably decreased the expression of β‐catenin in the colon cancer SW620 cells." (PMID 34547189, 2021). "However, NKD1 was well expressed in colorectal carcinoma tissues, and the possible role of NKD1 may have in the colon cancer cells is still obscure." (PMID 34547189, 2021). "Furthermore, the functions that NKD1 may have in colon cancer cells should be different from that NKD1 has played in the zebrafish." (PMID 34547189, 2021). "The results revealed that NKD1 and MYC were expressed at low levels in normal tissue and highly expressed in colon cancer tissues." (PMID 40675969, 2025). "In studying the correlation between NKD1 expression and the WNT signaling pathway, we found that NKD1 increased of β-catenin protein expression in colon cancer cells with high NKD1 expression." (PMID 40675969, 2025). "The results revealed a significant positive correlation between NKD1 and MYC gene expression in colon cancer tissues (p < 0.05)." (PMID 40675969, 2025). "Further studies revealed that in colon cancer cells, the MYC protein is degraded through the autophagy pathway and that NKD1 hampers this process by suppressing the interaction between the MYC and LC3B proteins." (PMID 40675969, 2025). "Taken together, these findings indicate that the NKD1/MYC signaling pathway promotes the proliferation, migration, and angiogenesis of colon cancer cells." (PMID 40675969, 2025). "Furthermore, this study also revealed that NKD1 could promote the colon cancer progression." (PMID 40675969, 2025). "Over-expression of NKD1 and AXIN2 correlates with the activated WNT/β-catenin pathway in cell lines and in the human colon tumor." (PMID 31434359, 2019). "The pcDNA3.1 plasmid, pcDNA3.1-PPARδ plasmid, pcDNA3.1-PPARδ + negative control siRNA (NC siRNA), and pcDNA3.1-PPARδ + NKD1 siRNA were consecutively transfected into colon cancer HCT116 and SW480 cells." (PMID 40675969, 2025). "Moreover, the expression levels of NKD1 and MYC in normal colon tissues and colon cancer tissues were determined via immunohistochemistry (IHC)." (PMID 40675969, 2025). "Our previous studies revealed that NKD1 promotes the proliferation of colon cancer cells; however, the effect of NKD1 on cell apoptosis has not yet been reported." (PMID 40675969, 2025). "Research has shown that NKD1 knockout significantly reduces the expression of the MYC protein and that there is a significant positive correlation between the expression of NKD1 and that of MYC in colon cancer tissues." (PMID 40675969, 2025). "The results revealed that the number of autophagosomes in HCT116-NKD1 cells was significantly lower than that in HCT116 cells, demonstrating that NKD1 could suppress the production of autophagosomes in colon cancer cells." (PMID 40675969, 2025).
colon carcinoma (continued). "In contrast, SW620-nkd1−/− cells demonstrated markedly lower MYC expression than that in SW620 cells, indicating that NKD1 increases MYC protein expression levels in colon cancer cells." (PMID 40675969, 2025). "We then wondered whether NKD1 affected the interaction between DVL and β‐catenin in the colon cancer cells." (PMID 34547189, 2021). "Thus, knocking out the NKD1 gene in colon cancer cells exceptionally inhibited cell proliferation, and this inhibition could be eliminated by overexpression of MYC, indicating that NKD1 promotes cell proliferation through MYC." (PMID 40675969, 2025). "Functionally, the PPARδ/NKD1/MYC signaling pathway increased colon cancer cells’ proliferation, migration and angiogenesis capabilities in vitro and in vivo, suggesting that NKD1 could serve as a potential therapeutic target for colon cancer diagnosis and treatment." (PMID 40675969, 2025).
gastric cancer (8 papers, 2010 to 2021). A primary or metastatic malignant neoplasm involving the stomach. "For example, exosomal miR-1290 from BGC-823 cells promotes the proliferation and invasion in gastric cancer via targeting mRNA of naked cuticle homolog 1 (NKD1), a transcriptional regulatory factor in GC and downregulating NKD1 expression." (PMID 33430032, 2021). "It has been demonstrated that NKD1 protein was down-regulated in gastric cancer, whereas its mRNA expression was up-regulated in colorectal adenomas and hepatoblastoma." (PMID 21599923, 2011). "NKD1 was infrequently methylated in primary gastric cancer, while NKD2 was frequently methylated." (PMID 26396173, 2015). "Conversely, NKD1 protein expression was down-regulated in some gastric cancer tissues." (PMID 21599923, 2011). "The authors found that miR-501-5p may directly bind and suppress several important repressors of the Wnt/beta-catenin signaling cascade [such as GSK3 beta, dickkopf-related protein 1 (DKK1) and naked cuticle 1 (NKD1)], which lead to hyperactivated signaling in gastric cancer cells." (PMID 32664914, 2020). "It has been reported that the pathway blocked by dickkopf WNT signaling pathway inhibitor 1 (DKK-1), naked cuticle homolog 1 (NKD1) and glycogen synthase kinase 3 beta (GSK3β) caused a robust reduction in the activity of wnt/β-catenin signaling and self-renewing capacity of gastric cancer cells." (PMID 27846906, 2016). "In conclusion, our study has revealed that miR-501-5p upregulation plays an important role in gastric cancer progression and miR-501-5p is a critical activator of Wnt/ β-catenin signaling by targeting DKK1, NKD1 and GSK3β." (PMID 27846906, 2016). "Collectively, our results suggest that miR-501-5p activates wnt/β-catenin signaling to enhance stem cell-like phenotype in gastric cancer by directly targeting DKK1, NKD1 and GSK3β." (PMID 27846906, 2016). "Herein, we demonstrated that miR-501-5p was substantially overexpressed in gastric cancer and induced hyper-activation of β-catenin/TCF via directly targeting DKK1, NKD1 and GSK3β." (PMID 27846906, 2016). "In this study, we detected the methylation status of NKD1 and NKD2 in human gastric cancer cell lines and primary cancer tissue samples." (PMID 26396173, 2015). "NKD1 and NKD2 were methylated in 11.7% (23/196) and 53.1% (104/196) in human primary gastric cancer samples." (PMID 26396173, 2015). "Methylation of NKD1 and NKD2 was examined in 196 cases of primary gastric cancer and 28 cases of normal gastric mucosa." (PMID 26396173, 2015). "Katoh investigated the expression of NKD1 and NKD2 in human cancer cell lines and primary gastric cancer." (PMID 20828404, 2010). "As NKD1 methylation did not appear to be a major event in human gastric cancer, we mainly focused on the mechanisms of NKD2 in gastric carcinogenesis." (PMID 26396173, 2015). "In human gastric cancer, EZH2 promotes the activation of Wnt/β-catenin signaling by down-regulating CXXC4 expression, and several other Wnt pathway antagonists, including NKD1, PRICKLE1, PPP2R2B, AXIN2 and SFRP5, were concordantly silenced by EZH2 in hepatocellular carcinomas." (PMID 27926488, 2017).
colorectal cancer (7 papers, 2008 to 2025). A primary or metastatic malignant neoplasm that affects the colon or rectum. "Paper reported that specific NKD1 mutations promote Wnt‐dependent tumorigenesis in mismatch repair deficient colorectal carcinoma." (PMID 34547189, 2021). "NKD1, a negative regulator, has been shown mutated in colorectal cancers." (PMID 20828404, 2010). "Bioinformatics showed that NKD1 highly expressed in the colorectal carcinoma tissues, which was confirmed by experiments." (PMID 34547189, 2021). "A previous study showed NKD1 expression in colorectal cancer and regulation by β-catenin in vitro, but our study is the first to examine its expression in adenomas and quantify the degree of induction." (PMID 18414471, 2008). "However, studies have also demonstrated that NKD1 is highly expressed in colorectal carcinoma tissues." (PMID 40675969, 2025). "Interestingly, the NKD1 expression levels are increased in fetal kidney and the colorectal cancer cells." (PMID 34547189, 2021). "Thus, NKD1 may be an important colorectal cancer biomarker and may function as a curative target for treatment of CRC." (PMID 34547189, 2021). "To determine whether this induction pattern is sustained throughout tumorigenesis, we performed real-time RT–PCR analysis of NKD1 and FZD3 in a series of 23 colorectal cancers." (PMID 18414471, 2008).